MORC4 (MORC family CW-type zinc finger 4)
Description:
Histone methylation reader which binds to non-methylated (H3K4me0), monomethylated (H3K4me1), dimethylated (H3K4me2) and trimethylated (H3K4me3) 'Lys-4' on histone H3. The order of binding preference is H3K4me3 > H3K4me2 > H3K4me1 > H3K4me0.
Synonyms: ZCW4; ZCWCC2; FLJ11565; dJ75H8.2
Tractability: Small molecule: a structure with a bound ligand is known. PROTAC: ubiquitination databases record sites on it.
Gene: Protein-coding gene on chromosome X (106,813,871 to 107,000,254, reverse strand). Ensembl gene ENSG00000133131.
Subcellular location: Nucleus
Subcellular location (Human Protein Atlas): Nucleoplasm
Gene Ontology:
Molecular function: histone H3K4me3 reader activity; protein binding; ATP hydrolysis activity; zinc ion binding
Biological process: chromatin organization
Cellular component: nucleoplasm; nucleus
Homologues: Orthologues: chimpanzee MORC4 (99% identical), rabbit MORC4 (92% identical), macaque MORC4 (92% identical), guinea pig MORC4 (86% identical), pig MORC4 (85% identical), dog MORC4 (84% identical), mouse Morc4 (81% identical), rat Morc4 (80% identical), zebrafish zgc:152774 (35% identical), zebrafish morc3a (33% identical), zebrafish morc3b (30% identical). Paralogues in human: MORC3 (36% identical).
Diseases named in the same sentence as MORC4 in open-access papers:
MORC4 is named in the same sentence as 24 diseases in open-access papers, as found by Europe PMC text mining. Sharing a sentence is not in itself a finding about the gene and the disease. The quoted sentences say what the papers report.
breast cancer (14 papers, 2020 to 2025). A primary or metastatic malignant neoplasm involving the breast. "The presence of CD206+ macrophages correlated with a pronounced lymphocyte infiltrate and subsets of CD206+ macrophages, expressing SERPINH1 and collagen 1, or MORC4, were unexpectedly associated with improved survival of breast cancer patients." (PMID 33377644, 2020). "Analysis of breast cancer tissues shows that MORC4 is negatively regulated by microRNAs, including miR-193b-3p, and elevated MORC4 levels are linked to poor survival." (PMID 33122719, 2020). "So far MORC4 expression has been described in breast cancer cells, where it is associated with poor survival." (PMID 33377644, 2020). "MORC4 has been associated with acute and chronic pancreatitis and inflammatory bowel disorders, including Crohn’s disease and ulcerative colitis, and more recently was found to be overly expressed in breast cancer cells and in diffuse large B cell lymphoma." (PMID 33122719, 2020). "Overexpression of MORC4 significantly increases the expression of BCL-2 in breast cancer cells and increases their resistance to adriamycin, 5-fluorouracil and cisplatin." (PMID 40070565, 2025). "MORC4 has a high expression in breast cancer cells and tissues, and knocking down MORC4 suppresses breast cancer cell activity and promotes their apoptosis." (PMID 39812044, 2025). "A recent study showed that baicalin is a potential anti-tumor drug that inhibits the tumorigenic behavior of breast cancer cells by reducing the expression of MORC4." (PMID 40070565, 2025). "Recent studies found that MORC4, as an oncogene, promotes the growth, migration, and invasion of breast cancer (BC) cells." (PMID 37692502, 2024). "Specific macrophage subsets co-expressing CD206 and SERPINH1 or MORC4 were connected with positive patient prognosis in breast cancer." (PMID 38893266, 2024). "MORC4 was found to be overexpressed in breast cancer tissues, and its downregulation by miR-193b-3p influences the proliferation of breast cancer cell via regulating apoptosis." (PMID 39980969, 2024). "MID2, as a promoter of STAT3, is interacted with protein MORC4, which regulates DNA damage response and gene transcription in breast cancer." (PMID 36925638, 2023). "Originally, miR-193b-3p was reported to be a tumor suppressor inhibiting several tumor-associated proteins, including the MYB oncogene in T-cell acute lymphoblastic leukemia and MORC4 in breast cancer." (PMID 36860299, 2023). "Morc4 is widely expressed at low levels in healthy tissues but is highly expressed in diseases such as acute and chronic pancreatitis, breast cancer cells, and diffuse large B-cell lymphoma." (PMID 36109779, 2022). "Studies have reported that overexpression of Morc4 increases breast cancer cell viability, migration and invasion, and reduces apoptosis in various breast cancer cell lines." (PMID 36109779, 2022). "Among the members of the MORC family, MORC4 is negatively regulated by miR-193b-3p and miR-338-3p in breast cancer, suggesting the significant value of miRNAs and MORC4 in cancer treatment." (PMID 34839357, 2021). "To analyze proliferation of macrophages, we stained primary human breast cancer sections of our cohort using immunofluorescence for co‐localization of Ki67 and MORC4." (PMID 33377644, 2020). "A recent study revealed that MORC4 might confer increased chemoresistance to breast cancer cells via STAT3-mediated MID2 upregulation." (PMID 37760252, 2023). "Other reports stated that silencing MORC4 could downregulate Bcl-2 levels and upregulate cleaved-caspase-3 and Bad levels in MDA-MB-231 cells, indicating a key role of MORC4 in mediating apoptosis in breast cancer." (PMID 34839357, 2021). "As for tumors, BA, a potent inhibitor of NF-κB, could inhibit migration and invasion in breast cancer by regulating miR-338-3p and MORC4 as well as reversing epithelial-to-mesenchymal transition by targeting β-catenin signaling." (PMID 32625089, 2020).
breast cancer (continued). "Moreover, the expression of miR-338-3p and MORC4 could be regulated by baicalin to suppress cell viability, migration and invasion and to promote apoptosis in breast cancer." (PMID 34839357, 2021). "MORC family CW-type zinc finger 4 (MORC4) is a member of the highly conserved MORC family, it has been observed to be highly expressed in multiple cancer, such as colorectal cancer, breast cancer, and lymphomas." (PMID 40070565, 2025). "In breast cancer, TRIM1 expression has been reported to be up-regulated via MORC4/STAT3-mediated transcription activation, which might be the reason that leaded to circTRIM1 overexpression in chemoresistant TNBC cells and tissues." (PMID 38755678, 2024). "Taken together, our data indicate that expression of MORC4, SERPINH1, and MHCII at protein level in combination with CD206 may serve as macrophage markers for survival in mammary carcinoma." (PMID 33377644, 2020). "In addition, MORC4 recruits STAT3 to the MID2 promoter and drives MID2 expression in luminal A/B breast cancer cells, which enhances the chemoresistance of breast cancer, indicating that MORC4 may be a therapeutic target for luminal A/B breast cancer therapy." (PMID 34839357, 2021). "Interestingly, MORC4 expression was selectively induced by IL‐4, whereas it was not affected by IFNγ, LPS, or a co‐culture with different breast cancer cell lines." (PMID 33377644, 2020).
chronic pancreatitis (5 papers, 2016 to 2022). A chronic inflammatory process causing damage and fibrosis of the pancreatic parenchyma. "Human Microrchidia 4 (MORC4) ATPase has been implicated in acute and chronic pancreatitis, inflammatory disorders and cancer." (PMID 33122719, 2020). "Human Microrchidia 4 (MORC4) is associated with acute and chronic pancreatitis, inflammatory disorders and cancer but it remains largely uncharacterized." (PMID 33122719, 2020). "Recent data show that the polymorphisms of PRSS1-PRSS2 (rs10273639) and MORC4 (rs12688220) are associated with recurrent acute pancreatitis and chronic pancreatitis." (PMID 30524475, 2018). "MORC4 has been implicated in several types of inflammatory diseases, such as Crohn’s disease, ulcerative colitis, tropical calcific pancreatitis, and acute/chronic pancreatitis." (PMID 34839357, 2021). "The polymorphisms at PRSS1-PRSS2 rs10273739, which influence trypsinogen expression, and MORC4 rs12688220, which associate with atypical localization of cludin-2 in pancreatic acinar cells, are associated with acute pancreatitis, related recurrent acute pancreatitis, and chronic pancreatitis." (PMID 30524475, 2018). "A recent genome-wide association study (GWAS) identified association with variants in X-linked CLDN2 and MORC4, and PRSS1-PRSS2 loci with chronic pancreatitis (CP) in North American patients of European ancestry." (PMID 26820620, 2016).
diffuse large B-cell lymphoma (2 papers, 2020 to 2022). "MORC4 has been previously identified through the immunoscreening of a testes cDNA library with diffuse large B-cell lymphoma (DLBCL) sera." (PMID 32992503, 2020).
lymphoma (2 papers, 2015 to 2025). A malignant (clonal) proliferation of B- lymphocytes or T- lymphocytes which involves the lymph nodes, bone marrow and/or extranodal sites. "Besides, among the MORC protein family, MORC4 is regarded as a potential lymphoma biomarker." (PMID 26098774, 2015).
cervical cancer (1 paper, 2025). A primary or metastatic malignant neoplasm involving the cervix. "According to our findings, the CHD6 gene exhibited higher expression than the RIMS1, MORC4, FMO5, TIAM1, and other genes in cervical cancer." (PMID 40847033, 2025).
colon cancer (1 paper, 2016). "Considering also the highest expression in adjacent tissues, three more genes show an agreement between expression and pathology location (the endometrial cancer genes MORC4 and TXNDC8 most highly expressed in the myometrium and colon cancer gene CDC27 most highly expressed in the ileum)." (PMID 26856619, 2016).
Hypercholesterolemia (1 paper, 2025). An increased concentration of cholesterol in the blood. "Consequently, MORC4 may also represent as a potential therapeutic target for the treatment of hypercholesterolemia." (PMID 40606021, 2025).
invasive carcinoma (1 paper, 2020). A carcinoma that is not confined to the epithelium, and has spread to the surrounding stroma. "However, macrophages expressing either MORC4 or SERPINH1 together with CD206 were positively correlated with patient survival, although their numbers did not significantly change in invasive carcinoma compared with DCIS or normal breast tissue." (PMID 33377644, 2020).
lipid metabolism disorders (1 paper, 2025). "This research aims to elucidate the function of MORC4 in hepatic lipid metabolism, thereby improving the understanding of the molecular mechanisms underlying lipid metabolism disorders." (PMID 40606021, 2025).
lymph node metastasis (1 paper, 2025). "However, the MORC4 expression was significantly different in the tissues derived from CRC patients with distant metastasis, different degrees of differentiation, lymph node metastasis, serum CEA level, and TNM stage (all P < 0.05)." (PMID 39812044, 2025). "However, MORC4 expression showed statistically significant difference in CRC tissues from patients with different TNM stage, serum CEA levels, with or without distant metastasis and lymph node metastasis." (PMID 39812044, 2025).
malnutrition (1 paper, 2016). Inadequate nutrition resulting from poor diet, malabsorption, or abnormal nutrient distribution. "Genetic susceptibility due to genetic mutations particularly in SPINK1, CFTR, CTRC, and CLDN2/MORC4 genes is the most important factor and not malnutrition or dietary toxins for idiopathic CP suggesting the term ‘tropical pancreatitis’ is a misnomer." (PMID 29868209, 2016).
metabolic syndrome (1 paper, 2025). A cluster of metabolic risk factors for CARDIOVASCULAR DISEASES and TYPE 2 DIABETES MELLITUS. "Consequently, MORC4 may represent a promising therapeutic target for the treatment of metabolic syndromes." (PMID 40606021, 2025).
myeloid leukaemia (1 paper, 2020). "High levels of MORC4 were demonstrated in healthy placenta and lymph nodes but with little or no expression in myeloid leukaemia cell lines such as K562, HL60 and MOLT-4." (PMID 32992503, 2020).
osteoarthritis (1 paper, 2024). A noninflammatory degenerative joint disease occurring chiefly in older persons, characterized by degeneration of the articular cartilage, hypertrophy of bone at the margins and changes in the synovial membrane. "A rare genetic variant in MORC4 has been associated with a 3.4 times increased risk of osteoarthritis (Open Targets Platform92, accessed 25.05.2022), and another MORC family member, MORC3, is involved in calcium homeostasis and maintenance of bone remodeling." (PMID 38594418, 2024).
osteosarcoma (1 paper, 2024). A usually aggressive malignant bone-forming mesenchymal neoplasm, predominantly affecting adolescents and young adults. "Although the roles of SP110, HHAT, MORC4, PAGE5, MAP7, and CAMK1G in osteosarcoma have rarely been reported, their involvement in other types of cancer has been revealed." (PMID 39980969, 2024).
tumor (6 papers, 2020 to 2025). "Meanwhile, MORC3 expression was positively correlated with residual tumor (P = 0.007) and lymphatic invasion (P < 0.001), and MORC4 expression showed positive relation to N-stage (P = 0.001), M-stage (P = 0.015), and clinical stage (P < 0.001)." (PMID 39812044, 2025). "Downregulation of MORC4 suppresses tumor growth by the induction of apoptosis." (PMID 33377644, 2020). "Additionally, the MORC2 promoter methylation was markedly increased in CRC tissues (P < 0.05), but the methylation of MORC1, MORC3, and MORC4 was significantly lower in the tumor tissues than in negative controls." (PMID 39812044, 2025). "As shown by further analysis of the relation between MORC4 and clinicopathological factors, the MORC4 expression was not significantly different in CRC tissues derived from patients with different genders, ages, tumor locations (left and right side), tumor diameters, or T-stage." (PMID 39812044, 2025).
MORC4 also shares sentences with these, for which no sentence is quoted: cancer (6 papers); pancreatitis (3); acute pancreatitis (2); colorectal cancer (1); endometrial cancer (1); nephrolithiasis (1); pancreatic cancer (1); T-cell acute lymphoblastic leukemia (1).